RN7SL302P (RNA, 7SL, cytoplasmic 302, pseudogene)
Gene: Miscellaneous RNA gene on chromosome 9 (124,607,159 to 124,607,458, forward strand). Ensembl gene ENSG00000241246.
Homologues: Orthologues: macaque Metazoa_SRP (95% identical). Paralogues in human: RN7SL1 (82% identical), RN7SL2 (82% identical), RN7SL3 (81% identical), RN7SL301P (81% identical), RN7SL650P (81% identical), RN7SL575P (80% identical), RN7SL665P (80% identical), RN7SL732P (80% identical), RN7SL172P (79% identical), RN7SL230P (79% identical), RN7SL91P (79% identical), RN7SL126P (79% identical), and 706 more.